RNU6-929P (RNA, U6 small nuclear 929, pseudogene)
Gene: Small nuclear RNA gene on chromosome 20 (56,785,981 to 56,786,087, reverse strand). Ensembl gene ENSG00000207158.
Homologues: Orthologues: chimpanzee U6 (98% identical), macaque U6 (93% identical), pig U6 (88% identical), pig U6 (84% identical), dog U6 (81% identical), pig U6 (78% identical), mouse Gm23308 (67% identical). Paralogues in human: RNU6-25P (93% identical), RNU6-36P (93% identical), RNU6-1 (92% identical), RNU6-2 (92% identical), RNU6-20P (92% identical), RNU6-3P (92% identical), RNU6-40P (92% identical), RNU6-4P (92% identical), RNU6-5P (92% identical), RNU6-6P (92% identical), RNU6-9 (92% identical), RNU6-12P (91% identical), and 1286 more.